UBR1 (ubiquitin protein ligase E3 component n-recognin 1)
Diseases named in the same sentence as UBR1 in open-access papers:
UBR1 is named in the same sentence as 33 diseases in open-access papers, as found by Europe PMC text mining. Sharing a sentence is not in itself a finding about the gene and the disease. The quoted sentences say what the papers report.
Johanson-Blizzard syndrome (14 papers, 2008 to 2026). "In humans, loss-of-function mutations in UBR1 result in Johanson-Blizzard syndrome (JBS), a rare autosomal recessive disorder characterized by a spectrum of developmental and neurological symptoms." (PMID 40167441, 2025). "Johanson-Blizzard syndrome (JBS) is a rare hereditary autosomal recessive disorder caused by a mutation in the ubiquitin protein ligase E3 component n-recognin 1 (UBR1) gene." (PMID 38606259, 2024). "For example, nonsense and frameshift mutations in UBR1, an E3 ubiquitin ligase that targets proteins for proteasomal degradation, cause the developmental disorder Johanson-Blizzard Syndrome." (PMID 36218234, 2022). "Several UBR1 missense mutations that moderately decrease Ubr1 activity cause less severe forms of Johanson-Blizzard Syndrome, suggesting a continuum of variant effects on UPS activity, similar to other genetically complex traits." (PMID 36218234, 2022). "Patients with the Johanson-Blizzard syndrome, who have mutations in the UBR1 gene leading to a loss-of-function of this protein, exhibit increased inflammatory infiltrates in the pancreas, leading to acinar cell destruction and pancreatic insufficiency." (PMID 32545869, 2020). "More recently, Ubr1 was also linked to the Johanson-Blizzard syndrome, an autosomal recessive disorder that involves pancreatic dysfunction and mental retardation, that has been suggested to be connected with impaired transcription factor degradation." (PMID 23209828, 2012). "Mutational inactivation of human UBR1, one of the E3 Ub ligases of the Arg/N-end rule pathway, is the cause of Johanson-Blizzard syndrome (see Introduction)." (PMID 21931868, 2011). "Johanson-Blizzard syndrome (JBS), also known as UBR1-related disorder, is a very rare autosomal recessive disorder caused by pathogenic variants in the UBR1 gene and characterized by significant phenotypic variability." (PMID 41846647, 2026). "Johanson-Blizzard Syndrome (JBS) is an autosomal recessive spectrum disorder associated with the UBR-1 ubiquitin ligase that features developmental delay including motor abnormalities." (PMID 40766417, 2025). "In humans, UBR1 is associated with a rare autosomal recessive genetic disorder called Johanson-Blizzard Syndrome (JBS) 2–6." (PMID 40766417, 2025). "In human, loss-of-function mutations in one of several UBR family proteins, UBR1, cause the Johanson-Blizzard Syndrome (JBS), a genetic disorder with multi-systemic symptoms including pancreatic insufficiency, growth retardation, and cognitive impairments." (PMID 29649217, 2018). "A proteasome inhibitor, MG132 has also been shown to increase the level of Ubr1, and this may act as a useful therapeutic strategy in pathologies caused due to reduced amount of Ubr1, like pancreatic dysfunctions and mental abnormalities, characteristics of Johanson-Blizzard syndrome." (PMID 28579943, 2017). "The gene for Johanson-Blizzard syndrome has been identified as ubiquitin protein ligase E3 component n-recognin 1 (UBR1), but the genetic mechanisms leading to the known phenotype are not fully understood as the gene is generally known to be involved in a proteolytic pathway of the ubiquitin system." (PMID 25506511, 2013). "In a cohort of patients with a highly suggestive clinical diagnosis of autosomal recessive Johanson-Blizzard syndrome (JBS; OMIM: #243800), MLPA analysis of the UBR1 was applied in patients with an unsolved genotype with negative results or only a single variant." (PMID 36672937, 2023). "Recent data suggest that in Johanson-Blizzard syndrome (OMIM 243800), the pancreas exhibits pancreatic exocrine insufficiency and does not express UBR1." (PMID 18366806, 2008).
pancreatic insufficiency (5 papers, 2008 to 2025). "Mutations in UBR1 result in Johnson-Blizzard syndrome, an autosomal recessive disorder characterized by pancreatic insufficiency, multiple malformations, and mental retardation." (PMID 39181686, 2024). "Ubr1 knockout mice exhibit decreased body weight or adipose tissue and an exocrine pancreatic insufficiency." (PMID 18366806, 2008). "As a result, it is possible UBR1 effects on glutamate homeostasis could contribute to both neurodevelopmental abnormalities and pancreatic insufficiency in patients with JBS." (PMID 40766417, 2025). "We also found an exocrine pancreatic insufficiency in Ubr1−/− mice that lacked Ubr1, a phenotype similar to but less severe than the pancreatic phenotype of JBS patients that apparently lack active UBR1." (PMID 21931868, 2011).
steatosis (4 papers, 2023 to 2025). Increased lipid within the cytoplasm of cells. "Work in these cellular models has also shown UBR1 regulates lipid homeostasis involved in hepatic and muscle steatosis." (PMID 40766417, 2025). "As an amino acid sensor regulating protein homeostasis, Ubr1 provides a new direction for the relationship between steatosis and nutritional sensors." (PMID 39210799, 2025). "The E3 ubiquitin ligase, Ubr1, acts as an amino acid sensor for liver and muscle steatosis and targets Plin2 for amino acid-dependent degradation." (PMID 39210799, 2025). "BCAAs like leucine and isoleucine bind and activate the E3 ubiquitin ligase Ubr1, degrading Plin2, and Ubr1 activity reportedly prevents steatosis in mouse livers and cultured human hepatocytes." (PMID 38732128, 2024). "It was demonstrated that the amino acid-induced Ubr1 activity was necessary to prevent steatosis in mouse livers and cultured human hepatocytes." (PMID 36624524, 2023).
fatty liver disease (2 papers, 2024). A reversible condition wherein large vacuoles of triglyceride fat accumulate in liver cells via the process of steatosis. "Leucine and isoleucine-induced activation of UBR1/2 ubiquitination is necessary to ameliorate hepatic steatosis and obesity induced by high-fat diet (HFD)." (PMID 39426289, 2024). "It has been shown before that leucine and isoleucine alleviate obesity- and HFD-induced hepatic steatosis in mice by inducing PLIN2 ubiquitination degradation via activating UBR1/2." (PMID 39426289, 2024).
pancreatitis (2 papers, 2020 to 2024). Inflammation of the pancreas. "Ubr1−/− mice are also more sensitive to induced pancreatitis, as shown by increased elastase activity and an elevated systemic inflammatory response upon cerulean dosing." (PMID 32545869, 2020).
amyloidosis (1 paper, 2021). A disorder characterized by the localized or diffuse accumulation of amyloid protein in various anatomic sites. "The MMSE‐correlated DEPs were mainly involved in amyloidosis (DNM1, UBR1, OPTN, FERMT2), CNS disorder (WIPF1) and energy metabolism (COA6, COX7C, PDPR) processes." (PMID 34528736, 2021). "Specifically, the proteins involved in amyloidosis, including optineurin (OPTN), ras‐related protein Rab‐21 (Rab21), dynamin 1 (DNM1), peroxisomal bifunctional enzyme (EHHADH), fermitin family homolog 2 (FERMT2), E3 ubiquitin‐protein ligase UBR1 were increased in T2DM‐MCI compared with T2DM‐nMCI." (PMID 34528736, 2021).
breast carcinoma (1 paper, 2021). "A former study manifests enhancing circ-UBR1 in breast cancer, and silencing one is available to repress advancement of breast cancer cell with curbed metastasis." (PMID 34787049, 2021).
chronic myeloid leukemia (1 paper, 2018). "Remarkably, previous studies also showed that the proteolytically-generated anti-apoptotic Lyn kinase protein fragment is targeted for degradation by the UBR1/UBR2 E3 ubiquitin ligases of the N-end rule pathway in chronic myeloid leukemia cells." (PMID 30384441, 2018).
developmental delay (1 paper, 2025). "Patients with JBS carry genetic variants in UBR1, display developmental delay, and miss motor development milestones 3,4." (PMID 40766417, 2025). "Because JBS patients have developmental delay, we expanded our studies to evaluate whether UBR-1 affects organismal development." (PMID 40766417, 2025).
gastric cancer (1 paper, 2024). A primary or metastatic malignant neoplasm involving the stomach. "Subsequently, we constructed a mutation landscape for the top 15 genes with the highest frequency of UBR1 mutations in gastric cancer." (PMID 39181686, 2024). "The study workflow detailed in this research elaborates on the role of UBR1 in gastric cancer and its potential clinical applications." (PMID 39181686, 2024). "In gastric cancer, UBR1 exhibited frequent genetic alterations including amplifications, profound deletions, and mutations, with a prevalence of 7.163% in three case studies." (PMID 39181686, 2024). "We utilized the TCGA database to identify differentially expressed genes related to UBR1 in gastric cancer, as depicted in the volcano plot." (PMID 39181686, 2024). "Protein expression levels of UBR1 in gastric cancer cell lines were determined by immunohistochemistry (IHC) and WB analysis." (PMID 39181686, 2024). "The results revealed that UBR1 is a potential biomarker for gastric cancer prognosis and immunotherapy, as it positively correlates with immune cell infiltration and immunotherapeutic response and can directly affect PDL1 expression." (PMID 39181686, 2024). "Multiple analyses were performed to determine the biological functions of UBR1 in gastric cancer (GC)." (PMID 39181686, 2024). "Furthermore, we analyzed UBR1 expression in gastric cancer cell lines." (PMID 39181686, 2024). "To elucidate the function of UBR1 in gastric cancer (GC), we used two siRNAs for cis-translational knockdown in AGS and MGC803 cells." (PMID 39181686, 2024). "This study evaluated the involvement of UBR1 in gastric cancer (GC) by examining the correlation between UBR1 expression and various clinical parameters, including age, gender, tumor grade, residual tumor grade, anti-reflux treatment, and TNM stage." (PMID 39181686, 2024). "qPCR and WB detected the mRNA and protein levels of UBR1 in GES-1, MGC803, MKN45, AGS, and HGC27 gastric cancer cells, confirming significant overexpression in these cell lines compared to human gastric mucosal cells (GES-1)." (PMID 39181686, 2024). "UBR1 expression in GES-1 and four gastric cancer cell lines was assessed using QPCR and WB." (PMID 39181686, 2024). "The Human Protein Atlas (HPA) database was utilized to identify UBR1-enriched pathways in AGS cells and to compare immunohistochemical differences between cancerous and adjacent non-cancerous tissues in gastric cancer." (PMID 39181686, 2024).
leukemia (1 paper, 2025). A malignant (clonal) hematologic disorder, involving hematopoietic stem cells and characterized by the presence of primitive or atypical myeloid or lymphoid cells in the bone marrow and the blood. "Transduction of UBR1 and UBR2 was sufficient to rescue leukemia cells from shSOD2-mediated sensitization to asparaginase while transduction of FBXW7 or STUB1 could not reverse this effect." (PMID 40131931, 2025).
lymph node metastasis (1 paper, 2021). "Via analyzing the clinical information table, it was discovered that circ-UBR1 was linked with Tumor Node Metastasis staging and lymph node metastasis, and elevated circ-UBR1 forecasted unpleasing prognosis." (PMID 34787049, 2021).
spinal cord injury (1 paper, 2023). Penetrating and non-penetrating injuries to the spinal cord resulting from traumatic external forces (e.g., WOUNDS, GUNSHOT; WHIPLASH INJURIES; etc.). "Gene Expression Omnibus database shows significantly downregulated expression of ubiquitin protein ligase E3 component N-recognin 1 (UBR1) in spinal cord injury (SCI)." (PMID 37094938, 2023). "This study offers compelling evidence for METTL14-mediated m6A modification of UBR1 mRNA in modulating neuron autophagy and apoptosis in spinal cord injury (SCI), which may provide novel targets for modern SCI therapies." (PMID 37094938, 2023).
stomach adenocarcinoma (1 paper, 2024). "The correlation between UBR1 and PD-L1 in stomach adenocarcinoma (STAD) was further validated using the TCGA database." (PMID 39181686, 2024). "This study aimed to investigate the potential of UBR1 as a prognostic biomarker and immunotherapy target for stomach adenocarcinoma (STAD) as well as its biological function and molecular mechanism in relation to the disease." (PMID 39181686, 2024). "The TIMER algorithm demonstrated a significant positive correlation between UBR1 expression and CD4+ T-cell infiltration in stomach adenocarcinoma (STAD) (P < 0.05)." (PMID 39181686, 2024).
cancer (6 papers, 2013 to 2024). A tumor composed of atypical neoplastic, often pleomorphic cells that invade other tissues. "According to KEGG and GSEA analyses, UBR1 was significantly associated with several cancer pathways, oxidative phosphorylation, and the TNF-NFκB pathway." (PMID 39181686, 2024). "This association was also confirmed using the EPIC algorithm, which linked UBR1 expression with various cancers." (PMID 39181686, 2024). "Using cBioPortal database analysis, we predicted the frequency of UBR1 mutations across various cancers." (PMID 39181686, 2024). "The results indicated that UBR1 protein is associated with various signaling pathways across different cancers." (PMID 39181686, 2024). "First, UBR1 was found to be overexpressed in various types of cancers, particularly GC, which is consistent with previous studies." (PMID 39181686, 2024). "Second, we used qPCR to detect UBR1 expression in 21 paired cancer and paraneoplastic tissue samples." (PMID 39181686, 2024). "Pan-cancer analysis was conducted using TCGA in conjunction with the GTEx database to determine UBR1 expression levels in normal and tumor tissues due to the limited number of normal tissue samples in TCGA." (PMID 39181686, 2024). "UBR1 is linked to various human diseases, including steatosis, pancreatic dysfunction, malformation, Johnson-Blizzard syndrome (JBS) and cancer." (PMID 39181686, 2024). "We investigated the genetic modifications of UBR1 in human malignancies due to its anomalous expression in cancer." (PMID 39181686, 2024). "In pan-cancer analysis using the TIME and EPIC algorithms, UBR1 was found to be associated with various immune cells, particularly CD4+ T cells." (PMID 39181686, 2024). "We measured the mRNA expression of UBR1 in 21 paired carcinoma and paraneoplastic tissue samples and found that UBR1 mRNA levels were significantly elevated in GC tissues (p < 0.001)." (PMID 39181686, 2024). "The inhibition of Arg/N-degron-dependent ubiquitin ligases, including UBR1, promotes apoptosis in various cancer cell types." (PMID 37094938, 2023). "Subsequently, we conducted a pan-cancer GSEA to identify the potential pathways influenced by UBR1." (PMID 39181686, 2024). "Previous research has also shown increased expression of cyclic UBR1 in breast and lung cancers." (PMID 39181686, 2024). "The finding that UBR1 acts on some misfolded nuclear receptors suggests it may have a role to play in a variety of human diseases of aging including cancer as well as Johanson–Blizzard syndrome." (PMID 24251101, 2013).
tumor (2 papers, 2021 to 2024). "Finally, we explored the correlation of UBR1 with Tumor Mutation Burden (TMB) and Microsatellite Instability (MSI) in malignancies, presenting our findings in radar charts." (PMID 39181686, 2024). "First, the ESTIMATE software predicted higher stromal and immune scores for both high and low expression of UBR1 in the tumor microenvironment (TME)." (PMID 39181686, 2024). "Stably expressed LC cell lines are constructing to explore the impacts of circ-UBR1/miR-545-5p/SSFA2 axis on tumor growth." (PMID 34787049, 2021). "Furthermore, UBR1 was significantly upregulated in tumors with sarcoid residual (R2) compared to those with complete tumor resection (R0)." (PMID 39181686, 2024). "Further tumor xenograft experiments in nude mice also confirmed that knockdown of circ-UBR1 could increase the expression of miR-545-5p, but decrease the expression of SSFA2, thus alleviating the progression of LC in vivo." (PMID 34787049, 2021). "Further tumor xenograft experiments in nude mice also testified that knockdown circ-UBR1 could elevate the expression of miR-545-5p but decrease the expression of SSFA2, thus alleviating the progression of LC in vivo." (PMID 34787049, 2021). "UBR1 expression showed significant correlations with clinical parameters such as age, gender, TNM stage, pathological stage, tumor resection, and anti-reflux therapy." (PMID 39181686, 2024).
inflammation (1 paper, 2022). Aberrant reaction of the microcirculation characterized by movement of fluid and leukocytes from the blood into extravascular tissues. "Notably we found TOPORS and UBR1 dysregulated in the USH1B organoids (GO:0010498); mutation of the former is a cause of autosomal dominant RP, and the latter promotes rhodopsin protein degradation in the OS via the UPS during retinal inflammation." (PMID 36240775, 2022).
UBR1 also shares sentences with these, for which no sentence is quoted: infection (2 papers); Obesity (2); anemia (1); autism (1); autism spectrum disorder (1); brain disorder (1); ciliopathy (1); Cognitive impairment (1); deafness (1); diabetes (1); dyslipidemias (1); glaucoma (1); Hepatic steatosis (1); Intellectual disability (1); Japanese encephalitis (1); lung carcinoma (1).